STAT3 (signal transducer and activator of transcription 3)
Diseases named in the same sentence as STAT3 in open-access papers (continued):
Sharing a sentence is not in itself a finding about the gene and the disease.
renal carcinoma (55 papers, 2009 to 2025). A carcinoma arising from the epithelium of the renal parenchyma or the renal pelvis. "The unmet need is to develop therapies/drugs targeting genes associated with STAT3 pathway in the renal cancer subtypes." (PMID 30863721, 2019). "Moreover, isoliquiritigenin inhibited the JAK2 and STAT-3-associated apoptosis in human renal carcinoma." (PMID 39574470, 2024). "p-STAT3 overexpression is often associated with a poor prognosis in several solid tumors, the progression of which is not linked to sex hormones, such as gastric, colorectal, lung and renal cancers." (PMID 35314590, 2022). "Earlier studies have shown that Signal transducer and activator of transcription 3 (STAT3) signaling plays an important role in the growth of renal cancers, and increased STAT3 activation has been associated with progression of pathological stages and worse overall survival." (PMID 30863721, 2019). "Interestingly, in an in vivo model of renal cancer, inhibition of YB-1 caused a concomitant decrease in STAT3 levels and increased sensitivity to cytokine IFN-α treatment." (PMID 26512918, 2015). "Beyond cytotoxicity, they reduce IL-10 secretion via STAT3 inhibition in cutaneous T-cell lymphoma and, in renal cancer models, decrease myeloid-derived suppressor cells while enhancing PD-1 blockade efficacy." (PMID 41296440, 2025). "Inhibition of STAT3 leads to induction of apoptosis, reduction of cell viability, and proliferation in renal cancer cell lines." (PMID 36230984, 2022). "Aberrantly phosphorylated STAT3 was observed in renal carcinoma, with notably elevated expression in the metastatic stage." (PMID 36230984, 2022). "Increased amount of kynurenine due to TDO overexpression contributed to the activation of aromatic hydrocarbon receptors in renal cancer cells and of STAT3." (PMID 36230984, 2022). "For example, an elevated expression of signal transducer and activator of transcription 3 (STAT3) has been defined in several tumor types including lung, pancreas and renal cancer." (PMID 33761971, 2021). "All these data demonstrated that the inhibitory activity of CHE in human renal cancer cells was, at least partly, mediated through the inactivation of STAT3." (PMID 31568643, 2020). "GATA3 overexpression significantly reduced STAT3 phosphorylation and attenuated the migration in both renal cancer cell and IL6-stimulated renal cancer cell." (PMID 31636361, 2020). "It has been demonstrated that STAT3 inhibitor WP1066 inhibited the growth of renal cancer cell lines or xenografted renal cancer cells." (PMID 33344220, 2020). "Expression of several genes varied substantially between the cancer subtypes suggesting significant differences in STAT3 pathway activation in these three renal cancer subtypes." (PMID 30863721, 2019). "Subsequently, the renal carcinoma cells were treated with Stattic (a STAT3 inhibitor) and Verteporfin (a YY1AP1 inhibitor) for 24 h." (PMID 31354472, 2019). "In this study, we compare and contrast the expression of clinically significant genes involved in the STAT3 pathway in different renal cancer subtypes by analyzing datasets from The Cancer Genome Atlas (TCGA)." (PMID 30863721, 2019). "STAT3 phosphorylation has been shown to affect HIF-2α levels in 786-O cells and HIF-1α and HIF-2α in Caki-1 renal cancer cells, and STAT3 phosphorylation at Tyr705 and Ser727 residues is increased in ccRCC tumors." (PMID 29464030, 2018). "It was also found that overexpressed-TGR5 activated by its ligand repressed STAT3 phosphorylation in renal carcinoma A498 cells." (PMID 28903349, 2017). "Inhibition of STAT3 pathway in ccRCC induces apoptosis, attenuates angiogenesis and metastasis in renal cancer mouse models." (PMID 29272308, 2017).
renal carcinoma (continued). "It has been reported that STAT3 is a potential modulator of HIF-1-mediated VEGF expression in human renal carcinoma cells, suggesting that STAT3 represents a promising therapeutic target for the treatment of RCC." (PMID 24324713, 2013). "To date, there is no data on the effects of simvastatin on regulating IL-6-induced JAK2/STAT3 signaling in renal cancer cells." (PMID 23690956, 2013). "We previously showed that AG490 inhibited STAT3 and induced apoptosis accompanied by the downregulation of Bcl-2 in renal cancer ACHN cells." (PMID 20461084, 2010). "We next examined the ways in which the viability and proliferation of renal cancer cells were affected when STAT3 activity was inhibited by WP1066." (PMID 20461084, 2010). "Also, in case experiments including incubation isoliquiritigenin with human renal carcinoma Caki cells, the inhibition of binding STAT3 to DNA results from the phosphorylation of STAT3 at both Y705 and S727 residues was observed." (PMID 38539427, 2024). "Their ability to modulate the inactivated Hippo pathway in mesothelioma, as well as inhibit AKT/mTOR, ERK and JAK/STAT3 pathways in renal cancer cells in vitro supported Meta-Analyses based studies showing a beneficial effect of statins for both overall survival and cancer-specific survival." (PMID 36293328, 2022). "Fibroblasts were reported to promote renal cancer cells to secrete IL-6 and phosphorylate STAT3." (PMID 36230984, 2022). "Attenuated STAT3 activity by si-IL6 sensitized renal cancer cells to doxorubicin." (PMID 36230984, 2022). "Furthermore, CVB inhibited the invasion and migration of renal carcinoma cells by interfering with the EMT through the suppression of the IGFBP3-AKT/MAPK/STAT3-Snail signalling pathway." (PMID 34512163, 2021). "Besides, the protein expression of STAT3 decreased in colorectal and renal cancer compared with normal tissues." (PMID 32486001, 2020). "STAT3 has also been reported to be involved in IL-6-induced proliferation of renal cancer cells." (PMID 28878571, 2017). "To further explore whether KRT8 promotes renal cancer cell migration and invasion through IL-11/STAT3, we overexpressed or knocked down IL-11 to conduct functional studies in renal cancer cells." (PMID 29100303, 2017). "We first tested whether RES (structure of resveratrol) inactivated STAT3 in Caki-1 and 786-O renal cancer cells." (PMID 26911335, 2016). "Moreover, statins was reported to inhibit renal cancer cell proliferation and metastasis through inactivating STAT3 signaling." (PMID 27122225, 2016). "STAT3 is required for HIF-1α activation in human renal carcinoma cells and in female MSCs." (PMID 25401104, 2014). "The contribution of STAT3 to cancer has been widely confirmed by numerous studies demonstrating dysregulated activation in a variety of human tumors such as breast, lung, pancreatic, ovarian, skin, and renal carcinomas, as well as many hematopoietic tumors." (PMID 19284568, 2009). "Thus, we hypothesized that canagliflozin might prevent renal cancer from progressing by regressing NLRP3/IL-6/STAT3 activity." (PMID 41068541, 2025). "We first tested whether WP1066 inactivated STAT3 in Caki-1 and 786-O renal cancer cells." (PMID 20461084, 2010). "Some studies have shown that CA suppressed hypoxia-induced STAT3 phosphorylation (in Y705), nuclear translocation of STAT3, HIF1α induction, and VEGF expression in human renal cancer cells." (PMID 40493253, 2025). "In renal cancer, the lncRNA SRLR contributes to sorafenib resistance by interacting with NF-κB and promoting IL-6 transcription, which activates the STAT3 pathway." (PMID 39512820, 2024). "Therefore, STAT3 signaling may partially influence IFI35-mediated autophagy in renal cancer cells." (PMID 35740527, 2022).
renal carcinoma (continued). "Exposure to increasing doses of CVB robustly reduced the p-AKT, p-STAT3, p-JNK, p-P38 and p-ERK levels in renal cancer cells in a dose-dependent manner." (PMID 34512163, 2021). "In renal cancer, lncARSR functions as miRNA sponge to competitively bind with miR-34 and miR-449, which can up-regulate AXL/c-MET and activate STAT3, AKT, and ERK signaling." (PMID 31892841, 2020). "Collectively, these results indicate that the IL6-increased STAT3 activation and MMP2 expression in renal cancer cells can be antagonized by concomitant administration of anti-IL6 antibody." (PMID 31636361, 2020). "HSP90 interacts with its client protein STAT3 and facilitates the binding of STAT3 to the TWIST1 promoter, leading to the transactivation of TWIST1 and EMT induction in ovarian and renal cancer cells." (PMID 32151082, 2020). "This suggests a similar amplifier loop in renal cancer, whereby IL-6 is induced by TKIs in RCC cells, consequently up-regulating VEGF expression via AKT and STAT3." (PMID 28903416, 2017). "In Caki-1 and 786-O renal cancer cells, 5 μM WP1066 prevented the phosphorylation of STAT3, and 2.5 μM WP1066 significantly (P<0.01) inhibited cell survival and proliferation." (PMID 20461084, 2010). "In this study, we showed that in Caki-1 and 786-O renal cancer cells, STAT3 inhibitor WP1066 inactivated the STAT3 signalling pathway and induced apoptosis, accompanied by reduced Bcl-2 expression." (PMID 20461084, 2010). "As a critical oncogenic molecule, miR-145 inhibits the proliferation, invasion, and metastasis of prostate, bladder, and renal cancers while inducing apoptosis in tumor cells by targeting and regulating oncogenic signaling pathways, such as PLD5, SWAP70, and STAT3." (PMID 40689207, 2025). "To determine the mechanism by which prolactin promotes ccRCC, we obtained phosphorylation and transcriptome databases of 110 renal cancer patients with CPTAC and found that PRL was positively correlated with p-STAT3 (p = 0.03, rho = 0.326) and p-JAK3 (p = 0.014, rho = 0.812)." (PMID 34539753, 2021). "Taken together, inhibiting the IL6/STAT3 signaling pathway and promoting GATA3 signals may be a therapeutic intervention for the treatment of renal cancer cell metastasis." (PMID 31636361, 2020). "IL6, another STAT3-activating cytokine, has been of much interest and antibodies that neutralize IL6 or block IL6 receptor (R) α are in clinical trials for ovarian, prostate, and renal cancers." (PMID 28186993, 2017). "STAT3 also inhibits HIF-1α degradation through competition with Von Hippel-Lindau tumor suppressor (pVHL) for binding to HIF-1α, thus stabilising HIF-1α protein levels in tumor cells, and p-STAT3 is a potential regulator of HIF-1α-mediated VEGF expression in renal carcinoma cells." (PMID 26501341, 2015). "One small-molecule STAT3 inhibitor, AG490, was originally selected from a group of tyrphostins screened for their ability to block Jak2 activity and has been shown to inhibit growth and induce apoptosis in some types of cancer cells, including renal cancer cells." (PMID 20461084, 2010).
T-cell lymphoma (55 papers, 2011 to 2026). "Four novel STAT3 mutations (D427H, E616G, E616K and E696K) were previously discovered in patients with mature T-cell lymphomas and reported to be damaging and gain-of-function (GOF) using FATHMM (functional analysis through hidden Markov models) assessment." (PMID 35752777, 2022). "In this study, we characterized the D427H mutation in the DNA-binding domain of STAT3 that was previously identified in patients with mature T-cell lymphomas, wherein it displayed hyper-phosphorylation and increased transcriptional response." (PMID 35752777, 2022). "STAT3 is also mutated in other T and NK cell neoplasias such as mature T cell lymphomas and aggressive NK cell leukemias." (PMID 34075200, 2021). "Whilst the STAT3 Y640F mutation was distributed across T-cell NHL cases, specifically 7 ATLL, 1 NK/T-cell lymphoma (NKTCL) and 1 MF, the IRF4 K59R mutation was only seen in ATLL patients, consistent with the restriction of signature 17 to these patients." (PMID 33597573, 2021). "The recurrent STAT3 Y640F mutation is found in different T-cell NHL including both CTCL and ATLL and confers constitutive STAT3 phosphorylation and increased transcriptional activity." (PMID 33597573, 2021). "Screening for known activating mutations in STAT3 or STAT5B identifies the presence of the STAT5BN642H driver mutation in feline enteropathy-associated T cell lymphoma in 7 out of 42 (16.67%) samples in total." (PMID 34680385, 2021). "Activating mutations of STAT3 have been frequently detected in NK- and T-cell lymphomas including ALK-negative ALCL." (PMID 32922661, 2020). "Treatment of two NK/T cell lymphoma cell lines that have activating STAT3 mutations with Stattic, a small molecule inhibitor of STAT3 that targets the SH2 domain, resulted in increased apoptosis." (PMID 31684088, 2019). "Mouse and human T cell lymphoma cells express PD-L1 in the steady state, and Stat3 binds to the promoter region of the Cd274 gene encoding PD-L119,22,23." (PMID 29728568, 2018). "Of the patients with mature T cell lymphomas, 18% had mutations in STAT3." (PMID 31684088, 2019). "Activating mutations in the SH2 domain of STAT3 are seen in other T cell lymphomas as well." (PMID 31684088, 2019). "Interestingly, an association between the JAK1 expression and the STAT3 activation has been reported in T-cell lymphomas." (PMID 30123428, 2018). "In addition, STAT3 mutations are more frequent in CD30+ than CD30− T-cell lymphomas." (PMID 32188095, 2020). "HIV+ persistent cells also expressed a STAT3-related anti-apoptotic and cytotoxic phenotype that resembles that of HIV-associated T cell lymphomas." (PMID 40236153, 2025). "This integration event results in a persistent population of HIV-infected T cells with a STAT3-driven gene signature characterized by enhanced anti-apoptotic phenotypes, closely resembling those observed in HIV-associated T cell lymphomas." (PMID 41009690, 2025). "HIV-1 DNA integration at the STAT3 locus in primary human CD4+ T cells directly drives T cell persistence and models the molecular pathogenesis of HIV-associated T cell lymphoma." (PMID 41009690, 2025). "The effects of HIV proviral insertional mutagenesis have been demonstrated in a handful of HIV-associated T cell lymphomas, where integration of an HIV provirus within intron 1 of STAT3, results in increased expression of the STAT3 protein." (PMID 40627772, 2025). "al. described several HIV + T cell lymphomas with clonal provirus integration at sites in STAT3 intron 1, near those in the GFP-High replicates described here." (PMID 40627772, 2025). "Durable tumor regression was observed in preclinical studies in patients with STAT3-dependent T-cell lymphomas following once-weekly intravenous injection of KT-333." (PMID 39169396, 2024). "STAT3 was efficiently and selectively degraded by KT-333 in four anaplastic T-cell lymphoma cell lines." (PMID 39169396, 2024).
T-cell lymphoma (continued). "Using site-directed mutagenesis, we investigated the phenotype of the point mutation D427H in the DNA-binding domain of STAT3, which was previously reported to exhibit GOF behaviour in NK/T-cell lymphoma patients." (PMID 35752777, 2022). "In patients with mature T-cell lymphomas and their subtypes, peripheral T-cell lymphoma (PTCL) and NK/T-cell lymphomas (NKTL), STAT3 is among the most frequently mutated genes." (PMID 35752777, 2022). "Two other antihistamines, clemastine and desloratadine, induced T-cell lymphoma cell apoptosis that are involved in downregulating signal transducer and activator of transcription 3 (STAT3) and cellular myelocytomatosis (c-Myc) activities." (PMID 32570749, 2020). "Previous studies show that PD-L1 expression is regulated by the transcription factor Stat3 in T cell lymphoma and NF-κB in myelodysplastic syndromes blasts." (PMID 32628668, 2020). "Given that STAT3 activation is such a prevalent feature in mature T cell lymphomas and that there are multiple mechanisms driving its phosphorylation and activation of downstream targets, these studies provide a plethora of potential therapeutic targets." (PMID 31684088, 2019). "For example, somatic mutations in the STAT3 gene were found in 40% of granular lymphocytic leukemia and T-cell lymphoma patients, with recurrent mutations located on the gene segment encoding the SH2 domain, which mediates STAT3 dimerization and activation." (PMID 31861720, 2019). "To seek an explanation for the more pronounced effects of combination treatment with PPP and ASP3026, we measured phosphorylation levels of IGF-IR, NPM-ALK, and STAT3 in NPM-ALK+ T cell lymphoma cells." (PMID 31340850, 2019). "Here we review the recent contributions to our understanding of the role of STAT3 in T cell lymphomagenesis, mechanisms driving STAT3 activation in T cell lymphomas, and current efforts at targeting STAT3 signaling in T cell malignancies." (PMID 31684088, 2019). "Components of the tumor microenvironment also play a role in maintaining STAT3 activation in T cell lymphomas." (PMID 31684088, 2019). "Targeting of STAT3 has shown promising results in pre-clinical studies in T cell lymphoma lines, ex-vivo primary malignant patient cells, and in mouse models of disease." (PMID 31684088, 2019). "In this review, we summarize the mechanisms of STAT3 activation and oncogenesis in B- and T-cell lymphomas and discuss potential therapeutic intervention." (PMID 31861597, 2019). "In a study of 91 patients with mature and immature T cell lymphomas, 31.8% were found to have activating mutations in the JAK/STAT3 pathway, with 13% having JAK3 mutations and 7.7% with JAK1 mutations." (PMID 31684088, 2019). "Accumulating lines of evidence suggests that the improper activation of signal transduction pathways (e.g. PI3K/AKT, Hedgehog, STAT3) are critical events in pathologies of T-cell lymphomas." (PMID 27275540, 2017). "Increasing evidences suggest that deregulation of signal transducer and activator of transcription-3 (STAT3) and suppressor of cytokine signaling 3 (SOCS3) is associated with the pathogenesis of T-cell lymphomas." (PMID 27275540, 2017). "The physical interaction of GLI1 and p-STAT3 in the three T-cell lymphoma cells were demonstrated by Western blot analysis of Co-IP." (PMID 27275540, 2017). "In the present study, the pro-survival transcription factor STAT3 was proved to be a new effector of Hh signaling-induced cellular protection in T cell lymphomas." (PMID 27275540, 2017). "In order to explore the potential connections between Hh/GLI1 and STAT3/SOCS3 pathways in T-cell lymphomas, those immunohistochemical results were incorporated into the Fisher's exact probability test." (PMID 27275540, 2017). "Firstly, there is negative-feedback between STAT3 and SOCS3, so aberrantly activated STAT3 stimulate the expression of SOCS3 in T-cell lymphoma." (PMID 27275540, 2017).